PRDM9 (PR/SET domain 9)
Diseases named in the same sentence as PRDM9 in open-access papers (continued):
Sharing a sentence is not in itself a finding about the gene and the disease.
B-cell precursor acute lymphoblastic leukemia (3 papers, 2014 to 2022). "Another study linking PRDM9 with cancer found that an excess of rare PRDM9 alleles were found in children affected by B-cell precursor acute lymphoblastic leukemia (B-ALL) and their parents." (PMID 24634223, 2014).
female infertility (2 papers, 2016 to 2024). Diminished or absent ability of a female to achieve conception. "In Prdm9-null mutants the number of activated H3K4me3 hotspots remains constant but they move towards gene promoters and to other PRDM9-independent H3K4me3 sites, and probably cause male and female infertility." (PMID 27104744, 2016).
aneurysm (1 paper, 2025). Bulging or ballooning in an area of an artery secondary to arterial wall weakening. "This study reveals that PRDM9 regulates ACTN2 expression through epigenetic modifications and interacts with PDLIM1 to mediate VSMC function and aneurysm progression." (PMID 40881324, 2025). "We hypothesize that low expression of PRDM9 inhibits H3K4me3, thereby reducing ACTN2 expression and subsequently affecting the progression of aneurysms." (PMID 40881324, 2025). "We hypothesized that low-expression PRDM9 suppressed H3K4me3, leading to reduced ACTN2 expression and contributing to aneurysm progression." (PMID 40881324, 2025).
cyst (1 paper, 2020). A sac-like closed membranous structure that may be empty or contain fluid or amorphous material. "Furthermore, the majority of germ cell clusters that sharply express PRDM9 and SPO11 might undergo apoptosis after cyst breakdown, leading to germ cell attrition." (PMID 33372178, 2020).
Hypertension (1 paper, 2021). The presence of chronic increased pressure in the systemic arterial system. "The SHR strain is an excellent rat model of human spontaneous hypertension and might also be a better model of meiotic DSB initiation than multiple laboratory mouse strains, because some SHR females lacking functional PRDM9 can produce offspring, as can at least one human female." (PMID 33910563, 2021).
Smith-Magenis syndrome (1 paper, 2025). Smith-Magenis syndrome (SMS) is a complex genetic disorder characterized by variable intellectual deficit, sleep disturbance, craniofacial and skeletal anomalies, psychiatric disorders, and speech and motor delay. "PRDM9 has been implicated in Smith-Magenis Syndrome (SMS), an autosomal disorder characterized by OFCs, depressed nasal bridge, hand polydactyly, toe syndactyly, clinodactyly of the 5th finger, micrognathia, etc43." (PMID 41510282, 2025).
X-linked ichthyosis (1 paper, 2017). "VCX encodes a small, highly charged protein of unknown function and has been previously studied for its involvement in PRDM9-related non-homologous recombination events and X-linked ichthyosis." (PMID 29072575, 2017).
cancer (242 papers, 2009 to 2026). A tumor composed of atypical neoplastic, often pleomorphic cells that invade other tissues. "PRDM9 in cancer has been linked to genomic instability, likely stemming from its known recombination function in meiosis." (PMID 41397959, 2025). "The PRDM9 gene, one of the most mutated genes with pan-cancer in the PR/SET domain gene family (PRDM), is associated with meiotic recombination." (PMID 38715006, 2024). "The Reactome tool identified 25 significant pathways associated with cancer, offering insights into the mechanistic underpinnings linking PRDM9 to cancer progression." (PMID 38003713, 2023). "Recent findings have implicated alterations in the PRDM9, particularly its zinc finger motifs, in the onset and progression of cancer." (PMID 38003713, 2023). "Aberrant PRDM9 expression appears in 32 different cancer types and differential RPDM9 expression is linked to genomic instability and transcriptomic landscape in tumors." (PMID 34201935, 2021). "PRDM9 is a PR domain containing histone methyl transferase which expression is normally restricted to the germline that has also been linked to a number of somatic cancers." (PMID 31848333, 2019). "In addition, mis-regulation of PRDM9 has recently been implicated in cancers, prompting the need for tool compounds to investigate these disease mechanisms." (PMID 31848333, 2019). "Similarly, PRDM9 was mutated with a high mutation rate in many cancer types, achieving values of 10.0% in UCEC, 14.2% in LUAD, and 15.4% in SKCM." (PMID 30347759, 2018). "Significance: Discovering PRDM9 as a H3K36 methyltransferase could lead to identifying the roles that PRDM9 may play in human fertility and susceptibility to cancer." (PMID 24634223, 2014). "PRDM9 is also upregulated in various cancer types and can mediate lysine methylation in histone and nonhistone proteins." (PMID 40111008, 2025). "In summary, our findings reveal a role of the testis-specific histone methyltransferase PRDM9 in cancer." (PMID 41397959, 2025). "Pan-cancer analysis of 32 different cancer types (TCGA) revealed PRDM9 upregulation in 20% of tumours compared to healthy matching tissue, with the highest PRDM9 activity detected in glioblastoma." (PMID 41397959, 2025). "Yet, the failure of meiotic gene-silencing is common in cancer, with over 200 cancer/testis genes, including PRDM9, found in tumours." (PMID 41397959, 2025). "A notable example is the PRDM9 protein, which shows variable expression in a significant subset of tumors across various cancer types." (PMID 39114444, 2024). "More recently, an analysis of human patient cancer samples revealed a significant upregulation of PRDM9 across many cancer types." (PMID 36972790, 2023). "A study made with 1879 cancer samples across 39 distinct cancer types discovered that PRDM9 was unexpectedly present in 20% of these tumors, even after applying strict gene homology adjustments." (PMID 37237485, 2023). "Though normally expressed in germ cells, PRDM9 is significantly upregulated across many cancer types." (PMID 36972790, 2023). "This detailed analysis not only confirms the pivotal role of PRDM9 in cancer development, but also unveils a complex network of biological processes influenced by its variations." (PMID 38003713, 2023). "The insights gained lay a solid foundation for future research aimed at deciphering the mechanistic pathways of PRDM9, offering prospects for targeted interventions and innovative therapeutic approaches in cancer management." (PMID 38003713, 2023). "In a study where PRDM9 expression was analyzed in 1879 cancer samples, PRDM9 was unexpectedly found to be expressed in 20% of these tumors." (PMID 35251135, 2022). "For example, in a comprehensive analysis of over 1,500 cancer samples across 39 cancer types, PRDM9 was found to be misexpressed in ~20% of tumors." (PMID 34481156, 2021).
cancer (continued). "Other interesting genes were PRDM9 and ZNF281, both of which play a role in DNA repair and have been shown to be responsible for frequent mutations in cancer." (PMID 34900699, 2021). "Taken together these pan-cancer studies strongly indicate a role of PRDM9 in oncogenesis possibly through its function in DSB repair." (PMID 32290321, 2020). "The meiosis‐specific histone methyltransferase gene PRDM9 has also been reported to be activated in cancers." (PMID 31102330, 2019). "Overall, PRDM2, PRDM3/MECOM, PRDM9, PRDM16 and ZFPM2/FOG2 were the most mutated genes with pan-cancer frequencies of protein-affecting mutations higher than 1%." (PMID 30347759, 2018). "The recombination enzyme PRDM9 is expressed exclusively in testis, but it is also expressed in a variety of cancer cell lines and samples and has been proposed as a cancer biomarker." (PMID 30060743, 2018). "Heterogeneity in the mutation frequencies was observed in the different tumor types with higher mutation rates found for PRDM3/MECOM, PRDM8, PRDM9, PRDM15, ZFPM1/FOG1 and ZFPM2/FOG2 in specific cancers." (PMID 30347759, 2018). "However, understanding the role of PRMD9 in these cancer types has been limited by incomplete knowledge of PRDM9 substrates." (PMID 36972790, 2023). "PRDM9 is involved in the expression of meiosis-specific cancer/testis genes." (PMID 34201935, 2021). "PRDM9 also appears to be active in at least a subset of cancer cells and may contribute to DSB formation at LAPs, suggesting another possible link between LAPs and HSs." (PMID 30060743, 2018). "PRDM9 has been identified as a meiosis-specific cancer/testis gene." (PMID 24634223, 2014). "However, despite PRDM9’s potential as an ideal and safe therapeutic target due to its germ-cell restricted expression, the functional role of PRDM9 in cancer is unknown." (PMID 41397959, 2025). "For SPO11 and PRDM9, which induce DNA strand breaks and create crossover events in cancer cells, one can speculate that their activation in cancer cells drives genomic instability and might therefore increase the sensitivity of these cells to DNA-damaging agents." (PMID 35251135, 2022). "There is increasing evidence that PRDM9 may be involved in oncogenesis and/or cancer evolution." (PMID 34201935, 2021). "We generated whole cell extracts (WCEs) from one of the cancer cell lines in which PRDM9 gene expression had been observed, NTERA-2, and a culture of non-cancerous primary human prostate smooth muscle (HPrSM) cells, in which no PRDM9 gene expression could be detected by RT-PCR." (PMID 22918178, 2012). "PRDM9, a lysine methyltransferase that catalyzes methylation at the H3K4 mark, has been identified as an oncogene with broad involvement in multiple cancers including breast cancer, liver cancer, and head and neck squamous cell carcinoma." (PMID 39765675, 2024). "We also noted seven genes marked with “caution” in PeCanPIE showing the truncation close to the C-terminal (CUX1, FLCN, FLG, MSH6, NSD1, PRDM9, and USP6), questioning its functional effects in the cancer context." (PMID 35406420, 2022). "PRDM9 and PRDM13 also showed exclusive expression in cancer, but their biological roles in these tumors are unclear." (PMID 26110843, 2015). "However, MRK-740 did not reveal any significant effect on proliferation of several cancer cell lines tested, indicating that at least for the cell lines tested their proliferation was not PRDM9-dependent." (PMID 35251135, 2022). "There are no detailed mechanistic studies on the relationship between PRDM9 and cancer." (PMID 34201935, 2021). "However, our data did not reveal any significant effect of MRK-740 on proliferation of several cancer cell lines we tested, indicating that at least for the cell lines tested their proliferation was not PRDM9 dependent." (PMID 31848333, 2019). "In addition, the histone modification H3K4me3, which is deposited by PRDM9 at DSBs, is not observed at recombination HSs in the cancer cell lines HepG2 and MCF-7." (PMID 30060743, 2018).
tumor (187 papers, 2010 to 2026). "Using Tumor Immune Estimation Resource (TIMER) data, we found patients with CREBBP, EP300, CHD7 mutations and PRDM9 amplifications associated with low B‐cell infiltration, potentially aiding tumor growth." (PMID 40693457, 2025). "We cannot, however, exclude the possibility that PRDM9 is active in at least a subset of the tumours under investigation and contributes to the increase in SV rates at LAPs." (PMID 30060743, 2018). "The cholesterol-lowering effect of PRDM9 inhibition, combined with its tumour-restricted expression, encourages the development of PRDM9-targeting drugs that could selectively target cholesterol in tumours." (PMID 41397959, 2025). "The observed increase in PRDM9 levels in mitotically arrested cells suggests that tumours treated with MTAs or drugs inducing mitotic arrest, such as Polo-like or Aurora kinase inhibitors, could upregulate PRDM9, enabling the emergence of persister cells and tumour recurrence." (PMID 41397959, 2025). "The authors showed that miR-30a has binding sites in the 3′UTRs of the tumour suppressor genes BNIP3L, PRDM9, and SEPT7, and that these target genes were upregulated following knockdown of miR-30a-5p." (PMID 34074015, 2021). "The tumor suppressor genes BNIP3L, PRDM9, and SEPT7 were each found to have direct 3’UTR binding sites with miR-30a-5p." (PMID 26472042, 2015). "Inhibition of miR-30a induced significant upregulation of BNIP3L, PRDM9, and SEPT7, while inhibition of miR-934 increased the expression of HIPK2, HOXA4, and MLL3, suggesting that the miRNAs exert negative regulatory effects on these established tumor suppressors." (PMID 26472042, 2015).
infection (11 papers, 2015 to 2025). The state of being infected such as from the introduction of a foreign agent such as serum, vaccine, antigenic substance or organism. "On day 7 of infection, the effector P14 T cell populations in the spleen that were deficient for Elf1 or Prdm9 displayed an increased frequency of memory precursor (KLRG1-CD127+) cells compared to the control population." (PMID 36156073, 2022). "Knocking down Prdm9 in CD8+ T cells using shRNA led to an increased frequency of KLRG1−CD127+/CD62L+CD127+ cells and a decreased frequency of CD62L−CD127− cells 7–21 days after LCMV Armstrong infection." (PMID 40111008, 2025). "Recently, it was reported that the knockdown of Prdm9 in CD8+ T cells by shRNA led to an increased frequency of KLRG1−CD127+/CD62L+CD127+ memory‐like CD8+ cells and decreased frequency of CD62L−CD127− effector‐like cells at 7–21 days post‐LCMV Armstrong infection." (PMID 40111008, 2025). "Furthermore, at day 21 of infection, the memory T cell population was comprised of an increased proportion of TEM (CD62L-CD127+) when Elf1 expression was knocked down and an increased frequency TCM (CD62L+CD127+) and a decreased frequency of t-TEM (CD62L-CD127-) when Prdm9 was knocked down." (PMID 36156073, 2022).
genetic disease (1 paper, 2021). "The assessment of PRDM9 diversity is important for understanding the complexity of human population genetics, inheritance linkage patterns, and predisposition to genetic disease." (PMID 34805134, 2021).
PRDM9 also shares sentences with these, for which no sentence is quoted: melanoma (28 papers); prostate carcinoma (26); colorectal cancer (20); lung carcinoma (19); multiple myeloma (17); glioma (15); schizophrenia (12); liver cancer (10); lymphoma (10); hepatocellular carcinoma (9); acute myeloid leukemia (8); neuroblastoma (8); neurodevelopmental disorder (8); breast tumor (7); colon cancer (7); gastric cancer (7); Intellectual disability (7); Kabuki syndrome (7); Sotos syndrome (7); Weaver syndrome (6); autism spectrum disorder (5); cervical cancer (5); chondrosarcoma (5); diffuse large B-cell lymphoma (5); malaria (5); pancreatic cancer (5); viral infection (5); acute leukemia (4); Anxiety (4); clear cell renal cell carcinoma (4).
A further 156 diseases each share a sentence with PRDM9 in 4 papers or fewer.